CSF1R (colony stimulating factor 1 receptor)
Diseases named in the same sentence as CSF1R in open-access papers (continued):
Sharing a sentence is not in itself a finding about the gene and the disease.
COVID-19 (10 papers, 2021 to 2023). A disease caused by infection with severe acute respiratory syndrome coronavirus 2. "Colony-stimulating factor 1 receptor (CSF1R) is important for proliferation, differentiation and survival of mononuclear phagocytes and has been identified as a key gene in COVID-19-related cardiovascular diseases." (PMID 38104081, 2023). "In a recent study, a significant decrease in membrane CSF1R was observed in COVID-19 patients, suggesting that the inflammatory status of patients can be determined by CSF1R analysis." (PMID 36851954, 2023). "Due to the distinct expression patterns between CD24 and CSF1R in the context of ICU settings in COVID-19 patients, we integrated these two immune-related genes into an index so-called “CD24-CSF1R index”." (PMID 36851954, 2023). "In COVID-19, a significant drop in membrane CSF1R is useful for stratifying patients, beyond the power of cell categories published thus far, which fail to capture COVID-19 specific events." (PMID 35915730, 2021). "There is specificity in CSF1R regulation, and in COVID-19, CSF1R analysis can indicate the inflammatory status of patients and overcome limitations of virology, bacteriology, and antibody tests." (PMID 35915730, 2021). "We have shown that changes in CSF1R expression in specific subsets can segregate COVID-19 patients with confidence." (PMID 35915730, 2021). "Dissecting the contribution of CSF1R expression to human blood and tissues, will enable us to develop anti-COVID-19, anti-cancer, and anti-inflammatory strategies, rescuing the MPS for therapy." (PMID 35915730, 2021). "In COVID-19, the CSF1R system is the most informative MPS marker and makes it possible to distinguish patients from other pulmonary diseases." (PMID 35915730, 2021). "Additionally, CD24 and CSF1R may also potentially serve as novel targets for antiviral drug development, which effectively assists COVID-19 treatment." (PMID 36851954, 2023). "In contrast, CSF1R was highly expressed in the COVID-19/non-ICU group (M = 5.259, SD = 0.923) compared to the COVID-19/ICU group (M = 3.921, SD = 1.062) (p = 1.155e-09)." (PMID 36851954, 2023).
lung adenocarcinoma (10 papers, 2013 to 2024). A carcinoma that arises from the lung and is characterized by the presence of malignant glandular epithelial cells. "The prognostic value of CSF-1R expression in TAMs was also evaluated in lung adenocarcinoma, where it was examined for its association with mortality rates and patient smoking status." (PMID 39457693, 2024). "Using 195 consecutive cases of lung adenocarcinoma, we examined the association of CSF1R expression with mortality and whether the prognostic association differs according to smoking status." (PMID 30065206, 2018). "Therefore, we conducted this study to examine the association of CSF1R expression in TAMs with mortality and determine whether this association differs according to smoking status in cases of lung adenocarcinoma using PID immunostaining." (PMID 30065206, 2018). "Therefore, we examined the association between high expression levels of CSF1R in TAMs and patient mortality and assessed whether the prognostic association differs according to smoking status, using 195 consecutive cases of lung adenocarcinoma." (PMID 30065206, 2018). "Given the growing popularity of immunotherapies, our findings, if validated, suggest the promising application of CSF1R-expressing TAMs as a biomarker or therapeutic target for the treatment of lung adenocarcinoma." (PMID 30065206, 2018). "Of the 195 cases of lung adenocarcinoma, we observed 65 cases (33%) in which CSF1R expression in TAMs was high using PID immunohistochemistry." (PMID 30065206, 2018). "Our results provide evidence for a potential interaction between CSF1R expression in TAMs and smoking status in the progression of lung adenocarcinoma." (PMID 30065206, 2018). "We observed high expression levels of CSF1R in TAMs in 65 of 195 (33%) cases of lung adenocarcinoma." (PMID 30065206, 2018). "Therefore, in order to investigating the role of TMSB10 in TAMs of lung adenocarcinoma, we isolated the tumor-infiltrating immune cells in xenograft tumors, and found that CSF1R+ TAMs and Foxp3+ Tregs were reduced in TMSB10 knockdown group." (PMID 33349268, 2020). "Its observational nature precludes the determination of a causal association between high expression levels of CSF1R in TAMs and mortality in never-smokers’ lung adenocarcinoma." (PMID 30065206, 2018). "In the current study, high expression levels of CSF1R were associated with high mortality in patients with lung adenocarcinoma; this prognostic association was stronger in never-smoking patients than in ever-smoking patients." (PMID 30065206, 2018). "In conclusion, the current study demonstrates that high expression levels of CSF1R in TAMs are associated with high mortality and that this prognostic association is stronger in never-smoking patients with lung adenocarcinoma than in ever-smoking patients." (PMID 30065206, 2018). "However, no previous studies have examined the association of CSF1R expression in TAMs with mortality or whether the prognostic association differs according to smoking status in lung adenocarcinoma." (PMID 30065206, 2018). "Analysis of our inducible H1299 cells revealed an absence of expression of the CSF1 receptor CSF1R in this lung adenocarcinoma background." (PMID 24019961, 2013). "The findings suggest that CSF1R-expressing TAMs may exert stronger tumor-promoting immunity in never-smoking patients with lung adenocarcinoma and serve as a therapeutic target in precision immunotherapies." (PMID 30065206, 2018). "CSF1R-expressing TAMs may exert stronger tumor-promoting immunity in never-smoking patients than in ever-smoking patients; therefore, never-smokers with lung adenocarcinoma may be particularly responsive to CSF1R-targeted therapies." (PMID 30065206, 2018).
Anxiety (9 papers, 2020 to 2025). Intense feelings of nervousness, tension, or panic often arise in response to interpersonal stresses. "Collectively, these results indicated that cognitive deficiency and anxiety-like behavior in Csf1r+/− mice can be rescued by sCSF1R replenishment." (PMID 41350870, 2025). "Treatment with PLX3397, a CSF‐1r inhibitor, significantly reduced microglia levels in all observed areas, including multiple regions associated with anxiety, namely the PFC, BLA, and vHIP." (PMID 40059451, 2025). "Also, within the top 40 differentially expressed genes, Csf1r, here observed to be downregulated in the pituitary and adrenal glands in response to long-term CR, has documented associations with anxiety-related behaviour, principally through its role in immunomodulation." (PMID 36364936, 2022). "Consistently, open field tests showed that Csf1r+/− mice spent significantly less time and traveled a shorter distance in the center than WT mice, indicating an anxiety-like behavior." (PMID 41350870, 2025). "Our observation corroborates with previous studies reporting that Csf1r+/− mice exhibited anxiety along with cognitive and sensorimotor deficit." (PMID 37542262, 2023). "For instance, administration of a Csf1r antagonist has been found to abrogate stress-induced anxiety-like behaviour in rodent studies through the depletion of microglia and concomitant reduction in neuroinflammation." (PMID 36364936, 2022). "Given that Csf1r+/− mice exhibit an anxiety-like behavior at the age of 9 months, we thus examined whether sCSF1R affects this emotional deficit." (PMID 41350870, 2025). "Furthermore, we studied a mouse model of chronic unpredictable stress (CUS) combined with a CSF1R inhibitor (CSF1Ri) (n = 9 ~ 10/group) on anxiety behaviours and microglial biology." (PMID 37542262, 2023). "Notably, pharmacologically depleting microglia (using the selective colony-stimulating factor-1 receptor [CSF1R] inhibitor, PLX5622) in acute withdrawal mouse models prevented withdrawal-induced anxiety-like behaviors." (PMID 39061923, 2024). "Anxiety or depression-like behaviors, validated by open-field tests or sucrose preference tests, were also observed in those Csf1r+/− male mice, but not in control males or female mice, which was consistent with those previous studies." (PMID 37259140, 2023). "Our past work and the work of others also demonstrated no impact of CSF1R blockade on anxiety 3 months after exposure to 4He particles." (PMID 32429943, 2020). "Similarly, mice treated with a CSF1R antagonist (PLX5622) did not display monocyte recruitment to the brain or anxiety after social defeat." (PMID 36549907, 2023).
colitis (9 papers, 2013 to 2024). Inflammation of the colon. "Heterozygous mutation in Csf1r has been shown to protect against pathology in a colitis model in mice." (PMID 28263993, 2017). "Specifically, CSF-1-deficient mice and male CSF-1R+/- mice were reported to be less susceptible to dextran sulfate sodium (DSS)-induced colitis, and treatment with a CSF-1 neutralizing antibody or a CSF-1R blocking antibody was highly efficacious in this same model." (PMID 31710624, 2019). "As pre-treatment of mice with neutralizing anti-CSF-1 antibodies protects them from DSS-induced colitis, we investigated whether loss of CSF-1R expression also afforded protection." (PMID 23451116, 2013). "Efficacy of JNJ-40346527 in TCT colitis was consistent with previous investigations of the role of CSF-1/CSF-1R in a second IBD model." (PMID 31710624, 2019). "In TCT colitis, the CSF-1R inhibitor, JNJ-40346527, effectively restored the CSF-1 and macrophage gene sets to baseline." (PMID 31710624, 2019). "We examined transcriptional data from CD mucosa for evidence of CSF-1 pathway activation and tested JNJ-40346527 (PRV-6527), a small molecule inhibitor of CSF-1 receptor kinase (CSF-1R), for its ability to inhibit disease indices in murine colitis." (PMID 31710624, 2019). "Although an increased colon:systemic exposure margin was achieved, the DSS colitis model results suggest a gut-restricted CSF1R inhibitor is only partially effective." (PMID 30192846, 2018). "In contrast to the protection we observed in male Csf1r+/− mice, heterozygous loss of PPRAγ gene in female mice exacerbated DSS-induced colitis." (PMID 23451116, 2013). "The fact that Csf1r+/− mice are indistinguishable from WT litter-mates when unchallenged, but protected when stressed indicates the importance of Csf1r gene dosage in DSS-induced colitis." (PMID 23451116, 2013). "In an examination of the acute inflammatory response, Csf1r+/− male mice were protected from the adverse affects of DSS-induced colitis compared with WT mice, while Csf1r+/− female mice were significantly less protected." (PMID 23451116, 2013). "Furthermore, to investigate the role of Carinh specifically in macrophages during DSS-induced colitis, we used an anti-CSF-1R antibody to inhibit the accumulation and infiltration of macrophages." (PMID 37055591, 2023). "While PCs are not normally found in colon, because we observed decreased proliferation and altered cell fates of SI epithelial cells in CSF-1 - and CSF-1R -deficient mice, we decided to examine the effects of CSF-1 and CSF-1R deficiency in normal colon and in mice with DSS-induced colitis." (PMID 23451116, 2013). "Our goal was to explore whether sufficient efficacy would be maintained with colon-localized CSF1R inhibition by comparing the effect of local delivery of small molecule CSF1R inhibitors to that of a known systemic CSF1R inhibitor in a preclinical mouse model of colitis." (PMID 30192846, 2018). "When both CarinhWTand CarinhKO mice were treated with the anti-CSF-1R antibody, they developed more severe colitis compared to CarinhWT controls that did not undergo anti-CSF-1R treatment." (PMID 37055591, 2023). "In the present paper, we investigated the expression of IL34, CSF1 and their shared receptor CSF1R in normal human ileum and colon, in inflamed and non-inflamed tissues of CD and UC patients, and in a mouse model of experimental colitis." (PMID 25896238, 2015).
epilepsy (9 papers, 2018 to 2025). A brain disorder characterized by episodes of abnormally increased neuronal discharge resulting in transient episodes of sensory or motor neurological dysfunction, or psychic dysfunction. "The fact is that CSF1R inhibition is one of the rare immune pathway whose modulation has demonstrated therapeutic benefit on epilepsy pre-clinical models." (PMID 33819288, 2021). "More precisely, to identify the structure of a CSF1R-regulating GRN in epilepsy, we took advantage of a set of 6 co-expression gene modules which were previously predicted (and, for one of them, validated) to be activated by this receptor." (PMID 33819288, 2021). "Here, we identified a gene regulatory network (GRN) involved in epilepsy that is controlled by inflammation and which regulates the expression and function of Colony Stimulating Factor 1 receptor (CSF1R), a therapeutic target for anti-epileptic drugs." (PMID 33819288, 2021). "We identified and characterized the dynamics of a CSF1R-regulating GRN in epilepsy and validated STAT1 and STAT3 as main regulators of this GRN." (PMID 33819288, 2021). "To develop a framework for identification of such alternatives, we here develop a mathematical model of a pro-inflammatory gene regulatory network (GRN) involved in epilepsy and centered around CSF1R." (PMID 33819288, 2021). "Taken together, these analyses point to a PLX3397-dependent reversion of module 18 expression in epilepsy toward health via Csf1R inhibition." (PMID 30177815, 2018). "As proof of concept, we applied CRAFT to epilepsy and predicted the tyrosine kinase receptor Csf1R as a potential therapeutic target." (PMID 30177815, 2018). "This study describes a general computational gene regulatory framework called CRAFT for drug target discovery, and the authors use CRAFT to identify the microglial membrane receptor Csf1R as a potential therapeutic target for epilepsy." (PMID 30177815, 2018). "For both these modules, Csf1R was predicted by CRAFT to “activate” the subset of genes in the module that are over-expressed in epilepsy." (PMID 30177815, 2018). "The predicted effect of Csf1R blockade in attenuating epilepsy seizures was validated in three pre-clinical models of epilepsy." (PMID 30177815, 2018). "In addition, the authors assessed the effect of a known Csf1R inhibitor in pilocarpine‐ and KA‐induced models and an ex vivo organotypic hippocampal slice culture, showing that blocking Csf1R attenuates epilepsy seizures." (PMID 34486831, 2022). "While CSF‐1R is expressed in some cells of the adult brain under homeostasis, namely microglia, it and its ligands have been shown to be upregulated and neuroprotective in mouse disease models of AD and epilepsy." (PMID 33350588, 2021). "Spatial and temporal information about the status of CSF1R signaling would be necessary to determine the extent of the contribution of this pathway to SE-induced microgliosis and the neuropathology and pathophysiology of epilepsy." (PMID 34149593, 2021). "As CSF‐1R is essential for the survival of the vast majority of microglial populations, it has recently become a commonly targeted receptor in drug development programmes for epilepsy and AD." (PMID 33350588, 2021). "Therefore, to date, a major focus has been to understand and potentially target CSF‐1R signalling in microglial cells in the context of neuropathologies such as AD and epilepsy." (PMID 33350588, 2021). "According to the CRAFT causal reasoning framework, small molecule blockade of Csf1R should therefore be therapeutic in epilepsy (i.e., reduce seizures) and restoration of module expression toward health by Csf1R inhibition should be predictive of therapeutic benefit." (PMID 30177815, 2018). "In this context, our previous study identified Colony Stimulating Factor 1 receptor (CSF1R) as a new therapeutic target, as its inhibition induced anti-inflammatory effects associated with a decrease in epileptic seizures in a pilocarpine mouse model of epilepsy." (PMID 33819288, 2021).
epilepsy (continued). "Moreover, Csf1R has not previously been linked to epilepsy, allowing the opportunity for novel target discovery." (PMID 30177815, 2018). "Also, we do not claim that the CSF1R pathway is the only contributor in neuro-inflammation as others have already been extensively validated in epilepsy, including IL-1β signaling." (PMID 33819288, 2021).
gastric cancer (9 papers, 2020 to 2024). A primary or metastatic malignant neoplasm involving the stomach. "The clinical importance of CSF-1R was reported in gastric cancer (GC)." (PMID 38254773, 2024). "The CSF-1/CSF-1R axis may be a biomarker for the clinical diagnosis of lymph node and peritoneal metastasis of gastric cancer and is a potential therapeutic target for gastric cancer." (PMID 34729112, 2021). "Studies have reported that elevated expression of CSF‐1/CSF‐1R significantly correlated with disease progression and with a poor overall survival (OS) and disease-free survival (DFS) of patients with gastric cancer." (PMID 34729112, 2021). "And CSF1R of CD8 + Tcell, CCL2, VSIG4 of M2 Macrophage, NRP1 of Th1, TGFB1 of Treg cell presented strong correction with PCOLCE expression in gastric cancer (P < 0.001; Cor value ≥ 0.40)." (PMID 33392251, 2020). "CSF1R of CD8 + Tcell, CCL2, VSIG4 of TAM, NRP1, TGFB1 of Th1 cell presented significantly correlate with PCOLCE expression in gastric cancer (P < 0.001; Cor value ≥ 0.40)." (PMID 33392251, 2020).
ischemia (9 papers, 2012 to 2023). A hypoperfusion of the BLOOD through an organ or tissue caused by a PATHOLOGIC CONSTRICTION or obstruction of its BLOOD VESSELS, or an absence of BLOOD CIRCULATION. "Colony stimulating factor 1 (CSF1), binding to CSF1 receptor (CSF1R), has been shown to reduce neuronal loss after hypoxic-ischemia- (HI-) induced brain injury." (PMID 33101590, 2020). "Together, these findings indicate that CSF1R and its related genes play a critical role in differential regulation of microglial activation following ischemia." (PMID 35154109, 2022). "Using GW2580 as a pharmacological inhibitor of CSF1R, we validated that microglial proliferation following ischemia was CSF1 receptor-dependent." (PMID 35154109, 2022). "A defective expression of CSF or CSF-1R in the brain makes it considerably more vulnerable to ischemia." (PMID 22272763, 2012). "We investigated the potential treatment effect of short-term CSF-1R inhibition on (GFAP-positive) astrocytes on days 14 and 35 after ischemia." (PMID 35115368, 2022).
multiple myeloma (9 papers, 2017 to 2024). "In myeloma, colony stimulating factor 1 receptor (CSF-1R) expressing tumor associated macrophages (TAM) have been shown to promote disease progression and CSF-1R inhibition prolongs myeloma-specific immunity, particularly after ASCT." (PMID 33777050, 2021). "CSF1R blockade significantly inhibits myeloma-associated macrophage polarization to the M2 type, implying that CSF1R-blocking antibodies could be a new tool for MM therapy." (PMID 35875135, 2022). "In one study of multiple myeloma in mice, the colony-stimulating factor 1 receptor (CSF1R)-blocking mAbs were paired with bortezomib and melphalan." (PMID 39682696, 2024). "CSF1R blockers in combination with bortezomib or melphalan have shown additional therapeutic efficacy in myeloma." (PMID 35672862, 2022). "Together, these data support the pathogenicity of CSF-1R-expressing macrophages and MDSCs in myeloma, particularly in the context of ASCT, and highlight a clinically tractable population to improve the depth and duration of immune responses after transplant." (PMID 33777050, 2021). "In multiple myeloma (MM), blocking CSF1R with CS7 inhibits the proliferation and differentiation of M2 macrophages and myeloma-associated macrophages (MAMs)." (PMID 32801364, 2020). "Furthermore, CSF1R-blocking abs contributes to reprogramming of TAMs for the treatment of myeloma." (PMID 35672862, 2022).